Y_RNA (Y RNA )
Gene: Miscellaneous RNA gene on chromosome 15 (34,314,728 to 34,314,828, forward strand). Ensembl gene ENSG00000207091.
Homologues: Orthologues: chimpanzee Y_RNA (100% identical), macaque Y_RNA (94% identical). Paralogues in human: Y_RNA (90% identical), RNY3 (89% identical), Y_RNA (89% identical), Y_RNA (88% identical), RNY3P1 (87% identical), Y_RNA (87% identical), RNY3P14 (86% identical), Y_RNA (86% identical), RNY3P10 (85% identical), RNY3P5 (85% identical), Y_RNA (85% identical), Y_RNA (84% identical), and 94 more.